CGAS (cyclic GMP-AMP synthase)
Diseases named in the same sentence as CGAS in open-access papers (continued):
Sharing a sentence is not in itself a finding about the gene and the disease.
melanoma (continued). "In our melanoma cell panel, eleven and seven cell lines expressed STING and cGAS, respectively, but only two cell lines were equipped with both molecules (IGR-39, LOX IMVI)." (PMID 34205379, 2021). "This study aimed at assessing the expression of TREX1 in human melanoma and the effects of its overexpression on the cGAS-STING pathway and human melanoma proliferation." (PMID 34519260, 2021). "In fact, melanoma cell lines showed a higher percentage of Nectin-1 and HVEM expression, while cGAS and STING were more prominently expressed in melanoma metastasis." (PMID 34205379, 2021). "cGAS-STING is indispensable in the therapeutic effect of PD-L1 or CD47 blockade against B16F10 mouse melanoma and MC38 colon adenocarcinoma in vivo." (PMID 32774773, 2020). "In established melanoma and colorectal cancer cell lines, STING signaling is repressed due, typically, to epigenetic silencing of cyclic GMP-AMP synthase (cGAS) or STING itself." (PMID 29050360, 2017). "Here, we identified a compound, dodecyl 6-hydroxy-2-naphthoate (DHN), that induces pyroptosis in melanoma cells by activating noncanonical cGAS/STING signaling." (PMID 40663398, 2025). "Moreover, the cGAS-STING signal is essential to regulate the antitumor response of PD-L1 blockade, whereas intramuscular delivery of cGAMP constricts melanoma growth and prolonged survival." (PMID 40296918, 2025). "It was previously reported that SRA737 + LDHU did not activate the cGAS-STING pathway in melanoma cell lines despite increased cytosolic DNA, suggesting other transcriptional pathways were likely to be involved." (PMID 40507298, 2025). "Carboplatin, a second-generation platinum antitumor drug derived from cisplatin, was also recently shown to suppress human melanoma through the activation of cGAS/STING pathway-mediated apoptosis, an effect facilitated through the upregulation of TREX-1 expression in human melanoma." (PMID 38482021, 2024). "Notably, the cGAS-S120A/T130A mutant abolished the increasing effect of cell transformation of JB6 Cl41 cells and colony growth of SK-MEL-2 malignant melanoma cells." (PMID 39424777, 2024). "The immune profile of B16-F10 murine melanoma cells was assessed by infecting these cells with BCG or stimulating them with agonists for different innate immune pathways such as TLRs, inflammasome, cGAS-STING and type I IFN." (PMID 38835781, 2024). "Several DNA sensors capable of recognizing cfDNA have been identified, including Toll-like receptor 9 (TLR9) within endosomes and cytoplasmic sensors like cyclic GMP-AMP synthase (cGAS) and absent in melanoma 2 (AIM2)." (PMID 39687793, 2024). "Mitochondrial DNA interacts with cyclic GMP-AMP synthase-stimulator of interferon genes, NOD-like receptor protein inflammasomes, and melanoma inflammasomes, which would induce invasive cytokine storms during SARS-CoV-2 infection and has a negative clinical impact." (PMID 37234160, 2023). "As DNA recognition receptors, cyclic GMP-AMP synthase (cGAS) and absent from melanoma 2 (AIM 2) also recognize DNA fragments." (PMID 37322517, 2023). "HFD and cGAS KO decreased B16 melanoma tumor regression and T cell infiltration, but not significantly additively." (PMID 36950761, 2023). "Considering the intimate involvement of the cGAS-STING pathway in antitumor immunity, we conducted further investigations to evaluate the in vivo antitumor efficacy of LiSmore using a murine model of melanoma." (PMID 37673917, 2023). "There are three main DNA sensors: TLR952, cyclic GMP-AMP synthase (cGAS), and Absent in Melanoma 2 (AIM2)." (PMID 37346090, 2023). "In summary, we provide the first evidence of a novel, isoform-specific role for AKT1 in therapy-induced senescence in human melanoma cells acting through NF-κB but independent of cGAS." (PMID 35158840, 2022). "Various DNA sensors such as TLR9, cyclic GMP-AMP synthase (cGAS), and absent in melanoma-2 (AIM-2)-like receptors have been recognized as potent DAMPs in the host cell." (PMID 34445645, 2021).
melanoma (continued). "However, no studies have assessed the role of carboplatin as a STING agonist and further investigations are required to provide a complete understanding of the role of carboplatin in melanoma suppression, and the activation of TREX-1 and cGAS/STING pathways." (PMID 34519260, 2021). "Targeting of TREX1/cGAS/STING pathway using carboplatin could be a novel and an effective therapeutic alternative for human melanoma." (PMID 34519260, 2021). "However, dysregulation of cGAS-STING observed here in both human and mouse melanomas appears to be a common feature of melanomas that contributes to the immune evasion of these tumours." (PMID 34359633, 2021). "In human colorectal and melanoma cell lines, a few mechanisms have been identified for aberrant cGAS‐STING signaling, including disruption of STING trafficking to the Golgi, epigenetic silencing via promoter hypermethylation, and downregulation of cGAS/STING protein expression." (PMID 40672434, 2025). "In cerebral ischemia and neurodegenerative diseases, cytosolic double-stranded DNA (dsDNA) activates the cyclic GMP-AMP synthase (cGAS) signaling pathway in microglia, promoting the expression of (Absent in melanoma 2) AIM-2/ NLRP3 and GSDMD, which leads to cell polarization and pyroptosis." (PMID 39994107, 2025). "Additionally, MDA5 detects long dsRNA, RIG-I detects short dsRNA, and cytosolic DNA sensors including absent in melanoma 2 and cyclic GMP-AMP synthase detect dsDNA." (PMID 38641810, 2024). "Cancer cells are known to resist activation of the cGAS-STING pathway, and it has been reported that silencing of STING or cGAS prevents the induction of antitumor immune responses in colorectal cancer, malignant melanoma, ovarian cancer, and KRAS-mutant non-small-cell lung cancer (NSCLC)." (PMID 34445736, 2021). "Indeed, a correlation between STING but not cGAS expression levels and viral oncolysis in melanoma and ovarian cancer cell lines has been reported." (PMID 34205379, 2021). "Therefore, we co-transfected THP-1 clones genetically deficient in cGAS, STING or Absent In Melanoma-2 (AIM2) with 3P-dsRNA:imDNA complexes." (PMID 27941826, 2016). "The lack of typical cGAS-STING-induced type I interferon expression in response to SRA737 + low dose HU treatment in vivo also suggested that this pathway was not responsible for the pro-inflammatory chemokine expression observed in two syngeneic melanoma models with this treatment." (PMID 40507298, 2025). "SPOP loss consistently increased STING protein levels, but not those of cGAS, TBK1, or IRF3, across human melanoma (A2058, HMCB, and MeWo), mouse melanoma (B16), human RCC (A498, 786-o, and UMRC6), mouse RCC (Renca), and HEK293 cells." (PMID 41148213, 2025). "In B78 melanoma, PIC alone did not significantly influence the expression of Ifnβ1, a marker of cGAS/STING activation of an IFN-I response, and elicited negligible effects on the Ifnβ1 expression in the radiated B78 cells when it was added after RT." (PMID 35999216, 2022). "The three major receptors responsible for DNA-driven immune responses include toll-like receptor 9 (TLR9), absent in melanoma 2 (AIM2) and cyclic-GMP-AMP synthase (cGAS)." (PMID 35961978, 2022). "Free exogenous viral DNA in the cytosol is recognized by either Z-DNA binding protein 1 (ZBP1), absent in melanoma 2 (AIM2), or cGAMP synthase (cGAS)." (PMID 27379086, 2016). "Both melanoma cell lines and the LN229 glioblastoma cell line expressed STING1, but did not express CGAS, which could again explain their sensitivity." (PMID 40955425, 2025). "The major nucleic acid sensors involved in DNA recognition are TLR9, cyclic GMP-AMP synthase (cGAS)-stimulator of interferon genes (STING), absent in melanoma 2 (AIM2) and Z-DNA-binding protein 1 (ZBP1), with the three latter ones being cytoplasmic DNA sensing mechanisms." (PMID 39090111, 2024).
melanoma (continued). "For instance, TLR-9, located in the cell endosome, recognizes dsDNA and DNA/RNA hybrids, and cytosolic sensors such as cGAS (cyclic GMP-AMP synthase) and AIM2 (absent in melanoma 2) also detect these molecules, leading to the synthesis of IFN-I and other cytokines." (PMID 37897003, 2023). "The cytosolic sensors cyclic GMP-AMP synthase (cGAS), interferon-activable protein 204 (IFI204), and absent in melanoma 2 (AIM2) recognize M. tuberculosis DNA, while retinoic acid-inducible gene-I (RIG-I), melanoma differentiation‐associated protein 5 (MDA5), and protein kinase R (PKR) detect RNA." (PMID 34248974, 2021). "However, when looking at the melanoma and glioblastoma cell lines, the highly sensitive U87 cell line did not express STING1 or CGAS, which could explain its sensitivity." (PMID 40955425, 2025). "For tumors lacking sufficient cGAS or STING, such as melanoma, colorectal and alternative lengthening of telomeres (ALT)-related cancer, targeting the cGAS-STING pathway for antitumor therapy may not be feasible, and oncolytic virus treatment might represent an alternative approach." (PMID 32854711, 2020).
breast carcinoma (94 papers, 2017 to 2026). "It is clinically important to perform future studies using other antibodies including 22C3 to examine the association between PD‐L1 expression in TC and STING or cGAS expression in breast cancer tissues." (PMID 39967410, 2025). "In ER+HER2- breast cancer, the abnormal inactivation of the cGAS-STING pathway is linked to endocrine therapy resistance." (PMID 40567603, 2025). "More importantly, we validated that the cGAS-STING pathway was associated with higher immune cell infiltration in breast cancer." (PMID 38167507, 2024). "Previous pre-clinical work in breast cancer has demonstrated that the underlying mechanism of innate immune response in DDIR-positive tumours is mediated by constitutive activation of the cGAS-STING pathway." (PMID 39395265, 2024). "Disruption of STING trafficking, regulated by the Rab7 and TBK1 axis, in breast cancer cells with PTEN loss also supports the role of PTEN on tumour immunogenicity through the cGAS-STING pathway." (PMID 38214828, 2024). "Conclusion: cGAS-STING-related genes risk model provides a new credible risk stratification method to improve the clinical prognostic assessment for breast cancer." (PMID 37051596, 2023). "Particularly, paclitaxel has been closely associated with the activation of the cGAS-STING pathway in breast cancer treatment, suggesting that targeting this pathway offers a novel approach for treating breast cancer." (PMID 37448962, 2023). "Targeting the cGAS-STING-associated mitochondrial apoptotic pathway is emerging as a novel therapeutic approach for breast cancer." (PMID 37448962, 2023). "Sinularin differentially upregulates ROS and causes oxidative DNA damage in breast cancer cells, potentially activating the cGAS-STING pathway." (PMID 37448962, 2023). "Together, these results indicate that elevated IFN-I response in both mouse and human breast cancer cell cultures is associated with activation of the cGAS-STING pathway." (PMID 36882786, 2023). "Consistently, the overexpression of RAD51 in breast cancer cells led to increase in DNA breaks and loss of cGAS expression." (PMID 36428789, 2022). "Indeed, activation of a cGAS-STING-mediated immune response has been shown to predict response to neoadjuvant chemotherapy in early breast cancer, and conversely the suppression of the cGAS-STING pathway is associated with trastuzumab resistant breast cancer." (PMID 41422117, 2026). "However, our results suggested that the overexpression of cGAS-STING pathway genes was paradoxically associated with poor outcomes in breast cancer, particularly by promoting immune evasion." (PMID 40861477, 2025). "Furthermore, the review critically examines current research directions and challenges associated with the cGAS-STING axis in breast cancer, while emphasizing recent breakthroughs in cGAS-STING-related studies." (PMID 40567603, 2025). "Importantly, the JAK/STAT1 signaling that is induced upon cGAS-STING activation has been associated with response to treatment in patients with breast cancer, including response to immunotherapy or chemotherapy." (PMID 38167507, 2024). "The cGAS‐STING pathway is rapidly emerging as a key for the treatment of solid tumour more specifically breast cancer." (PMID 41492185, 2026). "Here, we report a hyaluronic acid (HA)-coated manganese-platinum (MnPt) bimetallic nanozyme (HD@MnO2) that integrates enzymatic cascade initiation with cGAS-STING pathway activation to facilitate radioimmunotherapy for breast cancer treatment." (PMID 41821152, 2026). "Building on these findings, the study opens a new array for breast cancer treatment by seamlessly integrating redox‐responsiveness, biomaterial engineering and immune activation by cGAS‐STING pathway." (PMID 41492185, 2026). "IHC analysis of 70 breast cancer samples showed that most tumors had low cGAS and STING expression, based on a 0–3 scoring system where scores of 0–1 were defined as low and 2–3 as high." (PMID 40830678, 2026).
breast carcinoma (continued). "Here, we identify Poly(rC) Binding Protein 1 as a tumor suppressor that amplifies cGAS-STING signaling in breast cancer." (PMID 41501525, 2026). "The immune-related prognostic index (IRPI) they constructed shows that patients with high IRPI scores have poorer prognoses, further confirming that cGAS-STING pathway inhibition is a key mechanism driving immune evasion in trastuzumab-resistant breast cancer." (PMID 40567603, 2025). "In contrast to those reports, other studies have described tumor-promoting actions of cGAS-STING in breast cancer." (PMID 41299712, 2025). "As our understanding of the molecular mechanisms and roles of the cGAS-STING pathway in breast cancer deepens, the development of new immunotherapeutic approaches is likely to benefit." (PMID 40567603, 2025). "For instance, under growth-restricted conditions, activation of the cGAS-STING pathway helps breast cancer cells survive, while inhibition of this pathway triggers autophagy-dependent cell death mechanisms." (PMID 40567603, 2025). "Several recent studies have shown that the cGAS-STING pathway is involved in the therapeutic responses of breast cancer." (PMID 41299712, 2025). "In recent years, research on the cGAS-STING pathway in breast cancer has made significant progress, and its regulatory mechanisms and clinical significance have become increasingly clear." (PMID 40567603, 2025). "Further exploration is needed to clarify the specific roles of the cGAS-STING pathway in different breast cancer subtypes and to develop targeted therapeutic strategies." (PMID 40567603, 2025). "In Luminal breast cancer, the activation status of the cGAS-STING pathway has a complex interplay with the tumor immune microenvironment." (PMID 40567603, 2025). "This review systematically examines the role of cGAS-STING in shaping the breast cancer immune microenvironment, its therapeutic targeting, clinical translation status, and future research directions." (PMID 41573551, 2025). "After reviewing and organizing a large number of relevant studies, we have gained a comprehensive understanding of the role of the cGAS-STING pathway in different breast cancer subtypes." (PMID 40567603, 2025). "Under ultrasound, M@αM induce immunogenic tumor cell death in melanoma and breast cancer by releasing Mn2+ ions and activating the cGAS-STING pathway." (PMID 41007722, 2025). "The ferroptotic cascade not only intensifies DNA damage in 4T1 breast cancer cells but also synergizes with radiotherapy to activate the Mn2+-mediated cGAS-STING pathway, triggering robust systemic antitumor immunity." (PMID 40846966, 2025). "Here, we employed a metastatic breast cancer mouse model using the EO771 cell line that carries a high mutation burden to investigate the role of host cGAS, STING, and the IFN-I response in the anti-tumor effect of CTX." (PMID 40227734, 2025). "Team Dengrong from Sun Yat-sen University has found that the cGAS-STING pathway activity is significantly reduced in Luminal breast cancer cells, while AKT kinase is abnormally active." (PMID 40567603, 2025). "In this study, we explored the role of the cGAS-STING pathway in breast cancer immunotherapy resistance, particularly focusing on the pivotal role of the gene HOXC13." (PMID 40861477, 2025). "Recent report demonstrated that breast cancer cells with chromosomic instability rely on activation of inflammatory signaling mediated by cGAS and STING to survive." (PMID 40038300, 2025). "In this study, we aim to explore the role of the cGAS-STING pathway in breast cancer immunotherapy resistance." (PMID 40861477, 2025). "In Luminal breast cancer, the inactivation of the cGAS-STING pathway and the overactivity of AKT kinase form a vicious cycle, which is a significant cause of endocrine therapy resistance and metastasis in patients." (PMID 40567603, 2025). "Among the many potential target genes of miR-25/93, in breast cancer cells, CGAS was shown to be indirectly downregulated through NCOA3." (PMID 38389103, 2024).